PPARA (peroxisome proliferator activated receptor alpha)
Diseases named in the same sentence as PPARA in open-access papers (continued):
Sharing a sentence is not in itself a finding about the gene and the disease.
tumor (continued). "Inthis regard, we have shown that wild-type mice injected with isogenic PPARα expressing tumor cells respond to WY14643treatment and develop fewer and smaller tumors than untreated wild-type mice." (PMID 18725983, 2008). "Bone marrow transplantation and granulocyte depletion show that PPARα expressing granulocytes are necessary for tumor growth." (PMID 17327920, 2007). "It is unclear to what extent this requirement of PPARα for tumor growth is due to tumor cell-autonomous effects or its role in the host compartment of tumors, as shown by our current findings." (PMID 17327920, 2007). "Because TSP-1 can be expressed in several cell types, including tumor cells, endothelial cells and fibroblasts, we next determined the cellular origin for TSP-1 in the tumors of PPARα deficient mice." (PMID 17327920, 2007). "PPARα deletion is a second example for suppression of tumor growth by ablation of a gene in inflammatory cells; deletion of IKKβ in myeloid cells inhibits epithelial cell tumor growth." (PMID 17327920, 2007). "Conversely, the results underscore the importance of PPARα in the host tissue to sustain tumor growth." (PMID 17327920, 2007). "When TSP-1 was depleted by neutralizing antibody in PPARα KO mice, tumor growth was partially reversed." (PMID 17327920, 2007). "Together these findings support the importance of PPARα expression in host cells for tumor development." (PMID 17327920, 2007). "“In vitro” PPARγ and PPARα were evaluated in human tumor and normal cell lines, treated with natural or synthetic ligands." (PMID 17389773, 2007). "When re-transplanted to PPARα WT mice, these tumors grew rapidly to over 10,000 mm3 indicating that PPARα in the host can rescue PPARα −/− tumor cells." (PMID 17327920, 2007). "In contrast, the PPARα KO hosts suppressed metastatic growth in lung and liver, reducing the infiltration of the tumor cells from 50–70% of normal organ tissue area in the WT hosts to less than 10% tissue area in PPARα KO animals." (PMID 17327920, 2007). "In our experimental model the suppression of tumor growth in PPARα KO mice is mediated by leukocytes, mainly neutrophils." (PMID 17327920, 2007). "These two tumorigenic cell lines allowed us to distinguish between the tumor cell- autonomous role and the host tissue role of PPARα." (PMID 17327920, 2007). "It is highly plausible that the species differences in PPARα activity is at least in part responsible for the difficulties in demonstrating efficacy of PPARα agonists in a rodent model of human tumours." (PMID 16569247, 2006). "Furthermore, PPARα activation enhances the expression of angiopoietin-like protein 4, a key regulator of cellular motility, thereby promoting tumor invasion and metastasis." (PMID 41345744, 2025). "Elevated PPARα expression in CRC exhibits dual tumor-suppressive and oncogenic roles." (PMID 40718481, 2025). "PPARα is expected to serve as an important target for tumor immunotherapy." (PMID 40097417, 2025). "To investigate whether changes in cell viability are due to PPARα-mediated disruption of lipid metabolism, we conducted studies on lipid metabolism in tumor cells." (PMID 41285764, 2025). "The decrease in PPARα expression suggests that this transcription factor may also play a tumor suppressor role, particularly in mouse SCCs." (PMID 39195246, 2024). "In a murine melanoma model, the use of the PPARα agonist fenofibrate increased FA catabolism and subsequently enhanced the tumor-killing activity of CD8+ T-cells in the TME, significantly enhancing anti-tumor efficacy when combined with in vivo PD-1 blockade therapy." (PMID 39227970, 2024). "PPARα promotes tumor cell growth and inhibits anticancer immunity." (PMID 39660001, 2024). "Thus, myeloid cell PPARα depletion in A10-PPARα-Cre mice critically impairs both macrophage anti-tumor and anti-bacterial response." (PMID 38746124, 2024).
tumor (continued). "Whereas chemotherapy increases FAO related genes through peroxisome proliferator‐activated receptor α (PPARα), accelerated hypoxia‐inducible factor‐1α stabilization by tumor cells in obese mice impedes the upregulation of FAO, which contributes to its chemoresistance." (PMID 38145969, 2024). "Correlation analysis between the PPAR genes and the TME genes showed that PPARA was significantly negatively correlated with antitumor components, matrix remodeling and tumor proliferation rate, while PPARD was positively correlated with matrix composition (p < 0.05)." (PMID 38529307, 2024). "Accordingly, we hypothesized that the effects of PPARα on tumor cells may be attributed to abnormal lipid metabolism and the related expression of tumor suppressors." (PMID 37305395, 2023). "PPARα and PPARγ have been shown to inhibit tumor progression in several studies." (PMID 37645246, 2023). "The anti-tumor functions of PPARα and PPARγ are currently inconclusive and controversial." (PMID 37033970, 2023). "PPARα also participates in the reprogramming of tumour metabolism." (PMID 37987033, 2023). "Therefore, a combination of LXR agonist and PPARα inhibitor can synergistically enhance tumor growth inhibition." (PMID 37064872, 2023). "Tissue editing techniques disclose that wide-ranging functions of PPARα/γ agonists may be on-topic focused for differentially unlocking tumor phenotypes." (PMID 38273846, 2023). "The role of PPARα/γ expression in tumor cells for response to tumor tissue editing approaches remains open, especially as metronomic chemotherapy may enhance PPARγ expression in stress response to metronomic chemotherapy." (PMID 38273846, 2023). "PPARα reportedly functions as a tumor suppressor through its effects on lipid metabolism; however, the involvement of PPARα in the development of EMC remains unclear." (PMID 37305395, 2023). "Recently, Bi’s group has discovered that PPARα, a ligand-activated transcription factor that regulates lipid metabolism and tumor progression, also activates CPT1C expression by binding directly to the promoter region of CPT1C, indicating that CPT1C is a novel downstream target gene of PPARα." (PMID 36693836, 2023). "Therefore, it is evident that the influence of PPARα on tumor progression varies depending on tissue type and difference in its ligand." (PMID 38189049, 2023). "Among them, PPARA is an oncogene, which is consistent with our observation, so we speculate that β-elemene exerts tumour suppression in NSCLC through the oncogene PPARA." (PMID 37980372, 2023). "PPARA also appears to inhibit cell proliferation and tumorigenesis and induces degradation of the proto-oncogene Bcl2 which inhibits apoptosis in developing tumor cells." (PMID 36424525, 2023). "In addition to SREBP1, recent studies reported the involvement of cell cycle regulators in the PPARα-induced growth suppression of tumor cells." (PMID 37305395, 2023). "The tumor suppressor P63 represses PPARα in human keratinocytes." (PMID 35954274, 2022). "The multifaceted activity profile of PPARα/γ agonists in tumor tissue may be best exemplified in leukemia, both, in chronic myelocytic leukemias in combination with imatinib and in acute leukemias in combination with ATRA and low dose azacitidine." (PMID 35814409, 2022). "Furthermore, it was reported that LINC00467 exerted a tumor suppressor role by reducing cell viability, proliferation, migration, and invasion by regulating the miR-9-5a/PPARA signaling axis in HCC." (PMID 35719391, 2022). "For these reasons, we sought to inhibit both PPARα and γ, hypothesizing it could inhibit tumor invasion and proliferation." (PMID 34984327, 2022). "It was reported that fenofibrate, the peroxisome proliferator-activated receptor alpha (PPARα) agonist, could revert the ketogenic potentiality back to what it was originally in a tumor-bearing experimental animal model." (PMID 35326441, 2022). "In contrast to PPARα, PPARβ/δ clearly favors tumor angiogenesis." (PMID 35954274, 2022).
tumor (continued). "Previous studies related to RCC have shown that the PPARα, γ involved in the PPAR signaling pathway are involved in regulating the aggressiveness of tumor cells and may be used as prognostic markers of RCC." (PMID 36591111, 2022). "The absence of PPARα switches tumor-associated inflammation into tumor-suppressive inflammatory infiltrates, which inhibit tumor angiogenesis and tumor progression independently of the cellular tumor type." (PMID 35954274, 2022). "A single study using syngenic tumor inoculation experiments in PPARα knockout mice observed a reduction in tumor vascularization and proposed that PPARα might favor tumor angiogenesis." (PMID 35954274, 2022). "Among the three PPAR isoforms (PPARα, PPARβ/δ, PPARγ), PPARγ is the most studied to date due to its crucial role in carbohydrate and lipid homeostasis, regulation of apoptosis and tumor progression." (PMID 36499405, 2022). "In this study, in contrast to the robust gene expression classifier (ColoPrint), the PPARA expression level was not only considerably different between tumor and normal adjacent tissues, but its expression level was also found to decrease in certain stages of CRC." (PMID 35845311, 2022). "In addition, PPARα can inhibit DC dysfunction induced by lipid-rich exosomes secreted by tumor cells and improve the effect of immunotherapy." (PMID 36387147, 2022). "Due to its plethora of immunomodulatory and metabolic effects, PPARα might either promote or suppress tumor progression, provoking opposing effects on therapeutic outcomes." (PMID 35954274, 2022). "Clinically, tumor tissue editing can adequately design tumor tissues, a prerequisite for efficacious use of mTOR inhibitors in refractory metastatic uveal melanoma or refractory Hodgkin’s disease with metronomic low-dose chemotherapy and a PPARα/γ agonist." (PMID 35814409, 2022). "Although its effect on the tumor is unknown, tomelukast could target the PPARα and PPARγ to regulate carbohydrate and lipid metabolism, and exert an anti-inflammatory action." (PMID 34966691, 2021). "Taken together with our findings, the PPARα activity may be essential for the in vivo development of certain types of tumors and the early tumor engraftment reaction after metastasis." (PMID 33466690, 2021). "The role of PPARA in tumor initiation and development remains controversial." (PMID 33959155, 2021). "Similarly, in the same tumor type, inactivation of 5-lipoxygenase/leukotriene/PPARa pathway by MK886 Breg inhibitor resulted in a significant reduction of tumor growth and elimination of its metastatic potential." (PMID 34771546, 2021). "Such anti-angiogenic effects of PPARα agonists were lost in PPARα-deficient mice transplanted with PPARα-intact tumor cells, implying that PPARα activation in surrounding stromal cells, but not the tumor cells, attenuated tumor angiogenesis." (PMID 33946986, 2021). "Additionally, PPARα/γ agonists modulate the impaired lipid biosynthesis, which hinders anti-tumor efficacy of intratumoral natural killer T-cells (iNKT)." (PMID 33796020, 2021). "Similarly, in addition to PPARα, PPARγ agonists can also inhibit tumor growth by enhancing radiosensitivity." (PMID 34249928, 2021). "Interestingly, PPARα was downregulated in all tumor entities in comparison to healthy parotid tissue." (PMID 34360635, 2021). "Unlike CAFs, the activation of PPARα and PPARγ in macrophages favors an anti-inflammatory tumor-associated macrophage (TAM) phenotype." (PMID 33946986, 2021). "Accordingly, PPARα and PPARγ are considered tumor suppressor genes which inhibit tumor progression." (PMID 34109128, 2021). "Tumor cells can secrete fat-containing exosomes as a fatty acid carrier and activate PPARα of DCs to induce the synthesis of lipid droplets in DCs and enhance FAO, inducing the transformation of DC metabolism from glycolysis to OXPHOS, leading to the dysfunction of DC." (PMID 33732237, 2021).
tumor (continued). "PPARα appears to play a role in carcinogenesis; however, it may act as a tumour suppressor or an oncoprotein." (PMID 34572440, 2021). "Moreover, the anti-tumor effect of PPARα−/− DC vaccine further suggests the crucial role of PPARα in DC." (PMID 33086073, 2020). "One mechanism favoring tumor angiogenesis is the inhibition of PPARα by the NADPH oxidase NOX1." (PMID 32785018, 2020). "Importantly, the inhibition of PPARα effectively corrected the immune dysfunction of TIDCs and enhanced the anti-tumor efficacy of immunotherapies." (PMID 33086073, 2020). "In accordance with previous findings that TDEs substantially increased the expression of PD-L1 on DCs, we hypothesized that PPARα inhibition combined with PD-L1 blockade may initiate more powerful anti-tumor efficacy." (PMID 33086073, 2020). "Collectively, our findings indicate that TDEs, as FA carriers, negatively regulate DCs and targeting PPARα could be a promising anti-tumor strategy and of great therapeutic benefit." (PMID 33086073, 2020). "However, another study suggested that PPARα has a tumor-promoting activity in CRC cells through cross talk with the farnesoid X receptor pathway when there exist endogenous bile acids." (PMID 32071266, 2020). "All three PPARα agonists decreased Cyp2c38 and Cyp2c44 expression in tumours." (PMID 31791289, 2019). "Although the concentration of plasma TGs and the expression of acyl-CoA thioesterase 1 (Acot1), a downstream target gene of PPARα, were affected equally when mice were treated with the three PPARα agonists, these ligands showed different actions on tumour suppression and AA metabolism." (PMID 31791289, 2019). "Moreover, PPARα deficiency suppresses angiogenesis by producing excess thrombospondin (TSP-1) and also prevents tumor growth." (PMID 30717356, 2019). "Besides the paradoxical roles of PPARα, another nonnegligible issue impeding its use in clinical trials is that PPARα agonists typically increase the incidence of liver hepatomegaly and tumours through induction of cell proliferation and oxidative stress." (PMID 31791289, 2019). "Given that these are two opposite effects, we speculated that the inhibitory effect of PPARα agonists on tumour growth and angiogenesis depended on both EETs and 11-HETE levels." (PMID 31791289, 2019). "To test this hypothesis, we treated TNFα-induced senescent SF for 72 h with fenofibrate, a PPARα agonist recently been reported to have potent senolytic and senomorphic activity in senescent chondrocytes and tumour cell lines." (PMID 31708994, 2019). "There is broad consensus that tumor formation in rodents exposed chronically to peroxisome proliferators has little to no relevance for human health, as primates are less sensitive to the adverse effects of PPARα activators." (PMID 31215065, 2019). "Unlike PPARα, in some tissues, the hypoxia inducible factor downregulates PPARγ, leading to the loss of its tumor suppression activity." (PMID 29966227, 2018). "Some evidence has indicated PPARα activation as a possible trigger of ineffective tumor metabolism." (PMID 29966227, 2018). "PPARα antagonist impaired the tumor chemoresistance mechanism of GCs." (PMID 29966227, 2018). "In harsh environmental conditions PPARα was upregulated and could result in metabolic directives to ensure energy for tumor cells." (PMID 29966227, 2018). "It is also interesting to examine whether zaltoprofen can selectively activate not only PPARγ, but also PPARα or PPARδ, in terms of the anti‐tumor effects of zaltoprofen." (PMID 29573200, 2018). "The results showed that PPARα shRNA silence promoted tumor growth and increased tumor weight." (PMID 30519260, 2018). "We further detected the relationship of PPARα/Bcl2/autophagy signaling on tumor progression." (PMID 30519260, 2018). "In addition to the inhibition of PPARα on tumor progression, PPARα−/− mice inhibit tumorigenesis involved in increased endogenous angiogenesis inhibitor thrombospondin-1(TSP-1)." (PMID 28948004, 2017).
tumor (continued). "We confirm that glucose restriction contributes to tumor progression since the GSCs grown at low glucose levels were higly proliferating and paralleled by a significant increase of PPARα and decrease of PPARγ, thus confirming the opposite role of the two nuclear transcription factors in GSCs." (PMID 29312541, 2017). "miR-9 upregulation correlated with tumor invasiveness, cell growth, and tumor stage, but whether this was related to a decreased PPARα expression remains unclear." (PMID 28167956, 2017). "In addition to suppressing primary tumor development, PPARα activation by WY-14,643 inhibits metastasis to the contralateral lung and to the liver in an orthotopic NSCLC model." (PMID 28316613, 2017). "Previous studies have suggested that activation of PPARα can have anti-tumor effects." (PMID 27351284, 2016). "However, recent studies found reduced levels of PPARα in some tumor types, while PPARα agonists can suppress tumor growth." (PMID 27835866, 2016). "Furthermore, the PPARα agonist fenofibrate suppresses tumor growth in mice via decreased angiogenesis." (PMID 27351284, 2016). "In tumor growth inhibition, activated PPARα may bind directly to consensus DNA sequences, which inhibits c-Jun transcriptional activity and attenuates AP-1 expression." (PMID 25734181, 2015). "In PC cells, testosterone and 1,25-dihydroxyvitamin D3 (1,25(OH)2D3)-induced miR-17/92 downregulation was reported to alleviate the miRNA-mediated inhibitory effect on PPARA mRNA, thereby increasing PPARA transcript stability, promoting neutral lipid synthesis, and retarding tumor progression." (PMID 26690121, 2015). "In light of these findings, we propose that PPARα may act as a potential tumor suppressor against hepatocarcinogenesis." (PMID 25327562, 2014). "Tumor multiplicity was also significantly increased in PPARα-/- mice in comparison to WT mice." (PMID 25327562, 2014). "The differential activation of NF-κB in HCCs from PPARα-/- mice compared with WT animals may facilitate the cross-talk between hepatocyte and a tumor microenvironment that support tumor growth." (PMID 25327562, 2014). "Thus, in CRC PPARα seems to act as a tumor suppressor with antiangiogenic, anti-inflammatory, and, ultimately, antitumor activities." (PMID 22991505, 2012). "Although currently not included in clinical trials for anticancer therapy, the use of PPARα and agonists might also be worthy in targeting tumor stroma through antiangiogenic properties." (PMID 22654896, 2012). "We speculate that D6D is up-regulated by increased activity of SREBP-1c or PPARα in a tumor microenvironment characterized by hypoxia and aberrant energy metabolism." (PMID 23112819, 2012). "Interestingly, PPARα was detected preferentially in the cytoplasm of the tumor cells, and nuclear PPARα was found only in restricted areas of the tumor adjacent to the necrotic tumor tissue." (PMID 20569465, 2010). "This could be relevant, since fenofibrate via activation of PPARα is expected to force mitochondrial fatty acid β-oxidation in tumor cells, which are often characterized by mitochondrial dysfunction, and strongly rely on glycolysis as the main energy pathway." (PMID 20569465, 2010). "Todissect the mechanism by which PPARα suppressedtumour growth (i.e., direct effects on the tumour and/or angiogenesis), embryonicfibroblasts from PPARα (−/−) knockout mice were transformed with SV40 large T antigen andH-ras oncogenes then implanted into wild-type and PPARα−/− mice." (PMID 19043612, 2008). "However,topical PPARα agonists were only moderately protective against tumour promotion inmouse skin, despite the upregulation of PPARα in tumours comparedto normal epidermis." (PMID 19043612, 2008). "Recent studies have studied transplantable tumor growth in PPARα−/− or PPARβ/δ−/− mice." (PMID 18615187, 2008). "Tumor promotion was not related to the function of PFOA as a PP or PPARα agonist but was phenotypically linked to estrogenic gene signatures in trout liver." (PMID 18709148, 2008).